HLA-E (major histocompatibility complex, class I, E)
Diseases named in the same sentence as HLA-E in open-access papers (continued):
Sharing a sentence is not in itself a finding about the gene and the disease.
tumor (continued). "Several reports showed that CMV reactivation has strong effects on the KIR-receptor repertoire, and may enhance NKG2C+ NK cell activity against tumor cells expressing HLA-E." (PMID 26883100, 2016). "We demonstrated that HLA-E was expressed in the tumor tissues of 70.2% of the NB patients." (PMID 27322426, 2016). "As a consequence, tumor unique antigens may be presented also in the context of HLA-E, which may subsequently be recognized by cytotoxic T-cells." (PMID 27699181, 2016). "Furthermore, the function of HLA-E on tumor cells was assessed focusing on the effect of HLA-E on NK and LAK cell cytotoxicity." (PMID 27589686, 2016). "These factors are often downregulated in certain tumor entities and might influence the detection of HLA-E as complex with peptide and β2-m on the cell surface." (PMID 27589686, 2016). "HLA-E was expressed in 70.2% of the NB tumor tissues examined." (PMID 27322426, 2016). "However, these authors found that only HLA-G expression can serve as independent factor for OS, whereas the expression of HLA-E was significantly correlated with tumor metastasis." (PMID 27652273, 2016). "Thus the effect of tumor HLA-E expression on efficacy must be considered when using NK cells as immunotherapy in NB." (PMID 27322426, 2016). "Additionally, to estimate immune cell prevalence we used the average expression of the lymphocyte-specific genes GZMB, PRF1, CXCL13, IRF1, IKZF1, and HLA-E in each tumor sample." (PMID 27959926, 2016). "Because the down-regulation of HLA-E may inhibit tumor growth, HLA-E may be a new treatment target in NB and is worthy of further investigation." (PMID 27322426, 2016). "Furthermore, HLA-E expression in early breast cancer patients was also proposed as a prognostic marker for the outcome on tumor progression." (PMID 25401109, 2014). "Consequently, as 20–70% of NK cells express NKG2A, HLA-E expression by tumor cells impairs the anti-tumor activity of a predominant proportion of NK cells." (PMID 24715892, 2014). "HLA-G and HLA-E expression at the tumor cell surface might allow it to escape T and natural killer (NK) cell immune surveillance." (PMID 24363939, 2013). "HLA-E expression on the surface of tumor cells may allow the tumor cells to escape the immune surveillance by T and NK cells." (PMID 22200673, 2012). "Although the function of tumor-derived soluble HLA-E remains to be defined, we can postulate that these molecules could reinforce the host's immune suppression through inhibiting the functions of NK and T cells, and thereby favor the survival of tumor cells." (PMID 21712991, 2011). "We have also examined the influence of various cytokines on HLA-E production by tumor cell lines." (PMID 21712991, 2011). "Possibly, the balance between activating and inhibitory functions of HLA-E may differ in different tumor histotypes." (PMID 22032294, 2011). "Given evidence of HCMV presence in OC, this raises the possibility that HCMV-mediated MHC downregulation in infected tumours may further contribute to immune escape by shifting the balance toward HLA-E-mediated NK cell inhibition, compounding the tumour’s existing immunosuppressive mechanisms." (PMID 41463341, 2025). "This might be crucial for NK cell efficacy in high IFN-γ/HLA-E exposed tumor environment." (PMID 39349459, 2024). "This implies that HLA‐E may play a part in tumor immune escape." (PMID 38882209, 2024). "Interestingly, tumour cell surface expression of HLA-E is sensitive to downregulation by various clinically relevant pharmacological agents such as the XPO1 inhibitor selinexor, the proteosome inhibitor bortezomib, and the cyclin-dependent kinase inhibitor dinaciclib." (PMID 38223411, 2024). "Hence, the expression of HLA-E was inducible in tumor cells." (PMID 38007483, 2023).
tumor (continued). "Angiogenesis-related genes (FLT1, KDR, SPARC, INSR, ANGPT2, and FLT4) and MHC-I molecules (HLA-A, HLA-B, HLA-C, HLA-E, and HLA-F) were highly expressed in cluster 3 ECs, indicating that the cells may function as antigen-presenting cells and promote tumor parenchymal angiogenesis." (PMID 37533434, 2023). "Similarly, although HLA-E is frequently upregulated on tumor cells, it is in fact downmodulated by many viruses, such as herpesviruses, influenza A and B, cowpox virus, and vaccinia virus, by evolutionarily acquired mechanisms to interfere with MHC class I presentation of viral peptides." (PMID 37000496, 2023). "Thus, a suitable selection of NKG2A+ or NKG2A− Vδ2 T cells for expansion or engineering could help to narrow the Vδ2 T cell population according to the expression of HLA-E on tumor cells." (PMID 36831606, 2023). "Hence, the transition from NKG2A-mediated cell protection to NKG2C-induced cell lysis might be dependent on the actual HLA-E peptidome of the tumor." (PMID 37675109, 2023). "NKG2Anull NK cells exhibit higher cytotoxicity and increased ADCC activity and the potential to kill tumor cells expressing HLA-E or HLA-G; however, the proliferative capacity of NKG2Anull NK cells may be poor in HLA-Enull tumor tissues because of strong inhibitory signals." (PMID 37144558, 2023). "Furthermore, such CAR-NK cells could overcome inhibition by HLA-E or HLA-C expressed on tumor cells." (PMID 35585985, 2022). "Since tumor cells can regulate recognition signals and functionally modulate the expression of ligands for receptors on NK cells to mediate NK cell activity, we further investigated the dissimilarity in the expression of HLA-E and MICA/B in TNBC, RT-R-TNBC, and CD24−/low/CD44+ cells." (PMID 34502547, 2021). "Finally, we addressed the question whether HLA-E expression in EwS directly or indirectly via myeloid cells affects the functional antitumor responses of tumor-antigen specific CART." (PMID 34201079, 2021). "Additionally, studies have confirmed that HLA-E in human tumor cells and Qa-1 in mouse tumor cells could be significantly upregulated when simultaneously exposed to oxygen and glucose deprivation." (PMID 33422072, 2021). "Here, the absence of NKG2C may favor the risk of progression in B-NHL patients as HLA-E bearing tumor cells are not being recognized by NK cells, while the probability of an inhibition by the NKG2A receptor may rise." (PMID 33218185, 2020). "Thus, high HLA-E expression levels on the surface of tumor cells could inhibit the function of NK cells, which might be an important mechanism underlying tumor escape." (PMID 33115963, 2020). "NK cell-mediated ADCC may also be dampened by the engagement of checkpoint receptors, such as PD-1, or inhibitory HLA-specific receptors, as the interaction with NK cells could even induce tumor cells to increase the expression of HLA class I molecules, including HLA-G and HLA-E." (PMID 32272610, 2020). "Therefore, the effect of HLA-E on tumor prognosis is controversial." (PMID 27322426, 2016). "Therefore HLA-E overexpression in cancer in vivo might provide a potential tumor immune escape mechanism due to possible long term effects." (PMID 27589686, 2016). "However, the increased tumor burden might be correlated to a higher release of tumor-derived factor(s) that, in turn, can upregulate HLA-G and HLA-E production by BM stromal cells." (PMID 27610393, 2016). "In addition, increased HLA-E mRNA transcript levels in RCC lesions were associated with a worse prognosis of RCC patients and thus might have a predictive value in tumor progression of this disease." (PMID 27589686, 2016). "A high expression of HLA-E on the surface of target cells may protect them from NK cell mediated lysis, and this feature is commonly used as immune escape mechanism by virus-infected cells or tumor cells." (PMID 24741633, 2014).
tumor (continued). "A protective role of HLA-E in tumor cells was also underlined in patients with ovarian and cervical cancer, where tumor infiltrating CD8+ cytotoxic T cells (CTLs) showed an upregulation of the CD94/NKG2A inhibitory receptor, whereas NK cells were only found at very low numbers in the tumor tissues." (PMID 25401109, 2014). "Thus, HLA-E may provide key information to understand how virus-infected and tumor cells walk the thin line between immune surveillance and immune evasion." (PMID 22032294, 2011). "HLA-E, the ligand for NKG2A, showed higher epithelial-cell expression in tumour than adjacent tissue in sample-level summaries (median 1.06 vs. 0.57; BH-q = 0.035)." (PMID 42279307, 2026). "The lymph nodes are a key tissue site for drug resistance and tumour cell survival in CLL, and interestingly, selinexor overcomes high HLA-E expression induced by the lymph node-derived signals IL-4 and CD40L to enhance NK activation against CLL." (PMID 40291981, 2025). "Consequently, tumor cells may evade NK cell action through HLA-E overexpression." (PMID 40066089, 2025). "Increases NK cell-mediated lysis of tumour cells and ADCC due to downregulation of HLA-E on malignant B cells." (PMID 40291981, 2025). "With its higher surface expression, HLA‐E*01:03 inhibits NK cells via the NKG2A receptor more effectively than HLA‐E*01:01, in doing so reducing NK cell cytotoxicity against the tumour, resulting in increased relapse." (PMID 40764252, 2025). "Conversely, DCs in solitary primary tumours showed high expression of MHC class I molecules (HLA‐F, HLA‐E, HLA‐C, HLA‐B, HLA‐A)." (PMID 39601163, 2024). "We used antibody blocking to test the functional contribution of surface expression of these three prototypic NK cell inhibitory ligands—PD-L1, HLA-E, and MHC-I—on the killing of SK-N-SH tumor cells with PM21-NK cells." (PMID 39205244, 2024). "The blockade of the interaction between the HLA-E and the NKG2A receptor is an important drug discovery target since it can unleash the anti-tumor immunity of cytotoxic NK and CD8+ T cells." (PMID 38954358, 2024). "The inhibitory ligands PD-L1, HLA-E, and MHC-I are of particular importance in mediating NK cell killing of tumor cells by interacting with their respective receptors—PD-1, CD94/NKG2A, and KIRs—on the surface of the NK cells." (PMID 39205244, 2024). "This signaling cascade in target tumor cells can result in increased cell surface levels of select NK cell inhibitory ligands such as MHC-I and HLA-E." (PMID 39205244, 2024). "Specifically, the involvement of human leukocyte antigen (HLA) class I molecules (such as HLA‐A, HLA‐B, HLA‐C, HLA‐E and HLA‐F) and CD8A/B was consistently observed in the interactions between malignant cells and CD8 T cells in both tumour types." (PMID 39601163, 2024). "A very important factor in the control of tumour development and progression is the NKG2D molecule and its ligand HLA-E." (PMID 36980527, 2023). "Overall, HLA-E and -F coexpression correlated with high levels of HLA-A, TAP1/2 and B2M transcripts across tumor types." (PMID 38318504, 2023). "Boosting effector T cell anti-tumor response remains a challenge, in part owing to the expression of immune checkpoints and their ligands, such as NKG2A and HLA-E." (PMID 36831606, 2023). "In an in vivo study on cancer vaccination using mouse tumor models, the impact of therapeutic vaccines was greatly potentiated by disruption of the NKG2A/Qa-1b (conserved ortholog of HLA-E) axis even in a PD-1-refractory mouse model." (PMID 36960057, 2023). "Expression of HLA‐E in tumors suppresses NK cell function via the inhibitory receptor CD94/NKG2A on the surface of NK cells, resulting in immune cell resistance to tumor." (PMID 38069522, 2023). "Tumor cells upregulate their surface expression of inhibitory ligands such as CD111, CD112, CD155, CD200, PD-L1, HLA-E, and HLA-G." (PMID 38067178, 2023).
tumor (continued). "Chronic IFNγ signalling consistently induced expression of Qa-1b/HLA-E, a ligand for the cytotoxic lymphocyte inhibitory receptor NKG2a/CD94, in mouse tumour models, thereby conferring resistance to α-PD-1 therapy." (PMID 37752135, 2023). "The levels of HLA-E and UBE2Z were higher in lymphocytes, and their expression levels were correlated with the infiltration levels of B cell and T cell in tumor tissue." (PMID 35127943, 2022). "This has been supported by studies where high expression of HLA-E and NKG2A led to a high inhibitory signal, potentially leading to poor outcomes and tumor growth." (PMID 36072957, 2022). "On the other hand, other tumor cells try to increase the expression of MHC class I molecules, such as human leukocyte antigen (HLA)-E, which engages the inhibitory receptor NKG2A on NK cells." (PMID 36072957, 2022). "CAPZA1, HLA-E, IMPA2, NFE2L3, PLEKHO1, SIGLEC1, and UBE2Z were expressed at higher levels in tumor tissues, whereas EMX2, FGL2, FUCA1, and GRB2 were expressed at lower levels in tumor tissues." (PMID 35127943, 2022). "HLA-E is a ligand for the inhibitory CD94/NKG2A receptor and is reported to affect the functions of tumor-infiltrating CD8+ T cells." (PMID 35127943, 2022). "NKG2A/HLA-E: The cell surface molecule NKG2A, a member of a lectin family, is expressed by NK cells and in the tumor microenvironment also by CD8+ cells." (PMID 36231109, 2022). "In the TCGA dataset, the expression levels of CD2, HAVCR2, HLA-C, HLA-DRA, HLA-E, KLRK1, and TYROBP were all significantly downregulated in tumor tissues compared with para-tumor tissues." (PMID 35794593, 2022). "Most MHC I molecules, including HLA-A, HLA-C, HLA-E, HLA-F, TAP1, TAP2, and TAPBP (all P < 0.05), were upregulated in PTPRD/PTPRT mutant patients, indicating enhanced anti-tumor immunity in PTPRD/PTPRT mutant patients." (PMID 36248841, 2022). "HLA-E, ligand of NKG2A receptor, expression on tumor cells was detected, and 2 out of 3 tumor cells showed very low expression." (PMID 35479087, 2022). "HLA class II (ligand for LAG3), PD-L1 (ligand for PD-1), HLA-E (ligand for NKG2A), and CEACAM1 (ligand for TIM3) were all expressed on tumor organoids, suggesting that the opT cells were likely to be regulated by these checkpoint proteins." (PMID 34789550, 2021). "In IS-high samples, increased expression of PD-L1 (27.9% in IS-low vs. 48.2% in IS-high; p = 0.0336), HLA-E (73.8% vs. 90.7%; p = 0.0282) and PVR (70.5% vs. 87.0%; p = 0.0415) on tumor cells was detected." (PMID 34135436, 2021). "HLA-E was induced in EwS cells by IFN-γ stimulation in vitro and by GD2-specific CART treatment in vivo and was detected on tumor cells or infiltrating myeloid cells in a majority of human EwS biopsies." (PMID 34201079, 2021). "HLA-E and CD94 (KLRD1) was another one of the more significant immune cell-tumor interactions (on NK) during single-cell transcriptomic analysis of NPC." (PMID 33671917, 2021). "NK–tumor interactions included HLA-C/KIR2DL4, HLA-E/CD94 (KLD1), TIM3 (HAVCR2)/Galectin-9, CD96-PVR/Nectin1 and TIGIT-PVR/Nectin2." (PMID 33671917, 2021). "However, the clear mechanism of how HLA-E affects tumor environment is largely unknown." (PMID 34834481, 2021). "Epithelial-derived cancer cells, tumor macrophages, and CD141+ traditional dendritic cells promote the enrichment of HLA-E in carcinomas." (PMID 33692827, 2021). "Upregulation of peptide-loaded HLA-E, the ligand of CD94-NKG2A inhibitory receptor complex, was observed in tumor cells following exposure to IFN-γ." (PMID 33671917, 2021). "Takahiro Kamiya and colleagues revealed that HLA-E was overexpressed in multiple tumor samples, and anti-NKG2A PEBLs boosted the cytotoxicity of PB-NK cells against tumor cells expressing HLA-E, compared to the anti-NKG2A antibody Z199." (PMID 33193399, 2020). "HLA-E has been shown to be expressed on GBM cells and this HLA-E expression has been shown to prevent NK cell mediated lysis of these tumor cells." (PMID 33178210, 2020).
tumor (continued). "Tumor-infiltrating NK cells express high levels of NKG2A in comparison with peripheral or splenic NK cells, while HLA-E is upregulated on both hematopoietic and solid tumors." (PMID 32714324, 2020). "We found that HLA-E, a ligand of NKG2A, is expressed on both tumor cells and immune cells in the tumors of NSCLC patients." (PMID 32010126, 2019). "Blocking the NKG2A/HLA-E interaction therefore has the potential to restore NK cell and CD8+ T cell cytotoxicity of tumour cell targets." (PMID 30626155, 2019). "High HLA-E expression also induces NK cells to secrete IL-10 and TGF-β, which affects the promotion of tumor migration and invasion." (PMID 27322426, 2016). "Higher levels of HLA-E transcripts were detected in all RCC cell lines and tumor lesions, which were tested in comparison to normal kidney epithelium." (PMID 27589686, 2016). "Preclinical studies have suggested that tumor cells with high HLA-E expression inhibit NK-cell or CTL cytotoxicity, but blocking the binding between HLA-E and CD94/NKG2A receptor restores NK-cell and CTL cytotoxicity." (PMID 27322426, 2016). "Importantly, we found HLA-B, HLA-E, and PSMB10 all related to antigen presentation to be enriched among down-regulated genes in tumours with high LEF-1 expression suggesting an adverse impact of Wnt/β-catenin pathway on tumour recognition by immune cells." (PMID 40130164, 2025). "We observed consistently higher expression levels of MHC class I genes (HLA-A, HLA-B, HLA-F, HLA-E, B2M) in tumor cells from non-progressors to progressors." (PMID 39753553, 2025). "Numerous studies have highlighted the negative clinical implications of aberrant HLA-E expression by various solid cancers, hinting towards the possible immunosuppression of HLA-I-independent recognition and killing by tumour-infiltrating NK cells." (PMID 40361496, 2025). "Previous studies have shown that the CD94/NKG2/HLA-E signaling pathway negatively regulates NK-cell activity in HCC, which may contribute to tumor immune escape." (PMID 40534863, 2025). "High co-expression of HLA-E and NKG2A predicted poor survival outcomes in LGG patients, whereas low HLA-E and high NKG2C/E abundance predicted more favourable outcomes, suggesting a potential modulatory role of HLA-I on the tumour-infiltrating cytotoxic CD56dim NK cell subset." (PMID 40361496, 2025). "The team led by Weijian Liu in China utilized scRNA-seq technology to characterize the immunosuppressive tumor microenvironment profile of osteosarcoma (OS) and discovered that MHC-I (HLA-A, HLA-B, and HLA-E)/B2M genes were downregulated, indicating diminished tumor immunogenicity in OS." (PMID 40191187, 2025). "The augmented presence of immune ligand-receptor pairs such as IL-6, TNFSF13B, LGALS9-CD45, and HLA-E-KIR underscores the pivotal role of macrophages in modulating inflammatory responses, immune evasion, and reshaping the tumor microenvironment within the context of elevated LST1 expression." (PMID 41488617, 2025). "More recently, molecular studies have identified new targeted options and suggested that involvement of the PD-1/PD-L1 and HLA-E/NKG2A pathways could represent major therapeutic targets to restore immune system function and enhance anti-tumor responses." (PMID 41228348, 2025). "The upregulation of NKG2A on NK cells expanded ex vivo and on NK cells in the tumour-positive lymph nodes implies that the NKG2A:HLA-E axis could be targeted to improve NK cell function in the lymph nodes of patients with B-cell malignancies." (PMID 39200132, 2024). "This complex recognizes the tumor-cell-expressed non-classical MHCIb molecules HLA-E in humans or the Qa-1 molecule in mice." (PMID 39339180, 2024). "This has raised the prospect of a HIV-1 vaccine that mediates protection via HLA-E-restricted CD8+ T cells, and there is now great interest in exploiting HLA-E for both vaccine and immunotherapy strategies for both infectious diseases and tumours." (PMID 38571959, 2024).